CDK4 (cyclin dependent kinase 4)
Diseases named in the same sentence as CDK4 in open-access papers (continued):
Sharing a sentence is not in itself a finding about the gene and the disease.
cancer (continued). "At last, a limitation of our study is the testing of hybrid EMT cells in immunocompromised mice that does not take into account the interaction of cancer stem cells or CDK4/6-based therapy with the immune microenvironment." (PMID 40764669, 2025). "In gastrointestinal cancers, despite preclinical studies pinpointing positive effects on cancer inhibition in pre-clinical models, no positive clinical trials have been published with CDK4/6 inhibitors." (PMID 40699853, 2025). "CDK4/6 inhibitors induce a state of growth arrest, pushing a subset of cancer cells into senescence rather than apoptosis." (PMID 40563591, 2025). "Therapeutic interventions often exploit senescence: HSP90 inhibitor BIIB021 alters cancer-related genes, including those involved in senescence, to suppress BLCA growth, while CDK4/6 inhibitors such as palbociclib induce G1 arrest and senescence in RB + BLCA cells." (PMID 40781676, 2025). "Previous early trials of CDK4/6 inhibitors in gastrointestinal trials have not adequately selected for cancers with dependence on the targeted node." (PMID 40699853, 2025). "Combining epigenetic drugs with previously identified therapeutic vulnerabilities of BRG1-LOF cancers (such as SMARCA2-degraders or inhibitors of Aurora kinase, CDK4/6, oxidative phosphorylation, or others) will likely yield greater responses and warrants further investigation." (PMID 41008934, 2025). "Third, the lack of CDK4/6 inhibitors treatment limited the analysis of interaction effects between ICIs and CDK4/6 inhibitors on clinical outcomes of pan-cancer patients with CDKN2A ALT." (PMID 38822443, 2024). "Consistent with the effects on the cancer cell growth and survival, knockdown REV-ERBα strongly decreased expression of proteins important for growth, proliferation, and survival including MYC, CDK4, CDK6, CCND2/D3, and BCL2." (PMID 39383000, 2024). "SOX5 can promote cyclin D1/cyclin dependent kinase 4 (CDK4) complex, cyclin A and Rb phosphorylation, thereby reducing the percentage of G0/G1 phase cells and increasing the percentage of S phase cells, thereby promoting cancer cell proliferation." (PMID 38835366, 2024). "In cancer cells with RB loss such as MDA-MB-436, cell cycle progression is independent of CDK4/6 signalling, and cyclin E drives RB activity." (PMID 38350962, 2024). "miR-6883 was transfected into cells under normoxia or hypoxia and western blot analysis revealed that miR-6883 downregulates CDK4/6 and HIF1α in CRC and BC cells, pointing to miR-6883 as a promising therapeutic to target hypoxic tumors or HIF1α-deregulated cancer cells." (PMID 38344066, 2024). "Moreover, our study corroborates emerging data on the immunomodulatory potential of CDK4/CDK6 inhibitors, beyond their well-documented cell cycle arrest capabilities in cancer therapy." (PMID 38383657, 2024). "In cancer, PIN1 is frequently overexpressed and APCCDH1 frequently inactivated through phosphorylation, creating a wide therapeutic window for combined inhibition of CDK4 and PIN1." (PMID 38622115, 2024). "Together, these findings suggest that CDK4/6 inhibitors may synergize with SMURF2’s role in degrading HIF1α, presenting a promising combination strategy to target hypoxic pathways in cancer therapy." (PMID 39697237, 2024). "This suggests that a meaningful DNA damage response was not activated in CDK4/6i‐induced senescent cancer cells." (PMID 37854019, 2024). "In particular, CDK4 and CDK6, as well as cyclins D1 and E, are frequently altered in cancer." (PMID 38473265, 2024). "Even so, the proportion of patients in Hunan Cancer Hospital using CDK4/6 inhibitors was still not low." (PMID 39080554, 2024).
cancer (continued). "Gene expression analysis suggests that its mechanism of action may involve downregulation of cancer-related genes such as AKT1, BCL2L1, CCND1, CDK4, PLK1, and RHOA." (PMID 38751791, 2024). "Here, the authors show that MYC amplification induces CDK4/6 inhibitors resistance through transcriptional regulation of KLHL42, leading to RB1 degradation and targeting MYC overcomes CDK4/6 resistance in preclinical cancer models." (PMID 38424044, 2024). "Thus, the combination treatment with the CDK4 inhibitors abemaciclib and desipramine was more prominent in HCT-116 cancer cells than in H460 or MCF7 cells." (PMID 39000513, 2024). "Notably, tumors with elevated FOXM1 share many features with MPNSTs that are resistant to CDK4/6-MEK inhibition, most of which reflect extra-tumoral changes that suppress anti-cancer immunity." (PMID 39347707, 2024). "Aberrant activation of the phosphatidylinositol 3-kinase (PI3K)/AKT/mTOR signalling pathway has been identified as a key mechanism of resistance to treatment in cancer, including ET with or without a CDK4/6 inhibitor in MBC patients." (PMID 39322687, 2024). "In melanoma, overexpression of mutant BRAF promotes excessive proliferation of melanocytes, inducing the expression of P16INK4A, which subsequently inhibits the activity of CDK4 and CDK6, leading to hypophosphorylation of RB, cell cycle arrest, and thus inhibiting cancer development." (PMID 39048965, 2024). "CDK4 and CDK6 endorse the stabilization and activation of FOXM1 via phosphorylation leading to the activation of the G1/S phase gene expressions, the suppression of ROS, and the prevention of senescence in cancer cells." (PMID 37415164, 2023). "For instance, JNKs have been identified as CAK for Cdk4 in cancer cells, but such regulation has not yet been studied in neurons." (PMID 37108171, 2023). "Bioinformatics analyses of Gene Expression Profiling Interactive Analysis (GEPIA), Genomics of Drug Sensitivity in Cancer (GDSC) and Cancer Cell Line Encyclopedia (CCLE) datasets were applied to explore the relationship between YB-1/PARP1 protein levels and CDK4/6i IC50." (PMID 38037159, 2023). "Along with the FDA-approved CDK4/6 inhibitors, other CDK4/6 inhibitors (i.e., dalpiciclib, lerociclib, SPH4336, TQB3616, TQB3303, XZP-3287, HS-10342, PRT3645, FCN-437c, BPI-1178, GLR2007, and CS3002) have been tested in a variety of malignancies." (PMID 37626854, 2023). "In siliconsilicon analysis, we investigated the binding free energy (ΔG) of Neuropilins, an anti-cancer therapy targeting angiogenesis through the inhibition of vascular endothelial growth factor (VEGF), with various signaling pathways including CDK4, EGFR, RAS, BRAF, PI3K, and PTEN." (PMID 37885828, 2023). "For this reason, it has been suggested that a combination therapy using CDK4/6is and BCL2 inhibitors could inhibit proliferation and induce apoptosis of cancer cells." (PMID 37833875, 2023). "Given the finding that inhibiting CDK4 and CDK6 might retard cancer cell development, several CDK4/6 dual‐inhibitors come into being and show both good preclinical and clinical outcomes." (PMID 36127291, 2023). "Upregulated PEG10 expression is involved in oncogenesis and cancer progression prompting us to investigate whether PEG10 was involved in CDK4/6 inhibitor resistance." (PMID 38017459, 2023). "We discuss what is known about FOXM1 in MPNSTs relative to other cancers and how FOXM1 may be regulated by and/or regulate the most commonly altered players in MPNSTs, particularly in the MEK and CDK4/6 kinase pathways." (PMID 37686402, 2023). "Therefore, the CDK4/CDK6–RB axis is crucial to cell-cycle entry, and the vast majority of cancers destabilize this axis to promote proliferation." (PMID 37190133, 2023). "Consequently, CDK4 and CDK6 have become prime targets for therapeutic interventions in cancer treatment." (PMID 37593751, 2023).
cancer (continued). "While alterations in expression of DREAM complex members are documented in many cancers and correlate with cancer prognosis, its mechanistic role in CDK4/6 inhibitor resistance is not defined." (PMID 37035239, 2023). "However, we found that c-MYC S405A cancer cells had lower c-MYC, cyclin D1, and CDK4 expression than c-MYC WT cancer cells, while c-MYC S405E cancer cells had higher c-MYC, cyclin D1, and CDK4 expression than c-MYC WT cancer cells." (PMID 37596667, 2023). "Collectively, growing evidence demonstrates that targeting CDK4 and CDK6 through CDK4/6 inhibitors might have therapeutic benefits in various cancers and kidney diseases and should be further explored in the future." (PMID 37686364, 2023). "High-LPCAT1 expression could inhibit STAT1 expression, up-regulate CyclinD1, CyclinE, CDK4 and MMP-9, and decrease p27kip1 to promote cancer progression in HCC." (PMID 36307879, 2022). "The effect of MARS1-mediated CDK4 stabilization is more prominent in p16INK4a-negative cancers because MARS1 and p16INK4a appear to compete for interaction with CDK4." (PMID 35501376, 2022). "Therefore, these compounds are predicted to inhibit growth and induce apoptosis of cancer cells through their interactions with MMP12, MMP13, CDK4, JAK3, VEGFR1, VEGFR2, and KCNA3." (PMID 36106139, 2022). "These pieces of evidence support that PRC2 inhibitors could induce therapeutic response in cancer from different body location, and the combination of PRC2 inhibitor with PD-1 therapy and/or CDK4/6 inhibitors could be a valid clinic strategy." (PMID 35169119, 2022). "This study suggests that targeting AKT1 in combination with CDK4/6i represents a therapeutic strategy in which cellular senescence can be achieved without the release of pro-cancer factors." (PMID 35158840, 2022). "The genomic features that are linked to the responses of the two drugs are also biologically relevant; for example, EGFR is the upstream factor of PI3Ks, and the effectiveness of combined CDK4/6 (targets of CDKN2A) and PI3K inhibition has been shown in other cancer models." (PMID 35992090, 2022). "Neither CDK4/6 inhibitors nor oncolytic adenoviruses show high efficiency as monotherapy in the treatment of cancer." (PMID 35948546, 2022). "The main two combinatorial strategies involve growth factors that either activate upstream of the cyclin D-CDK4/6-Rb pathway or pathway members, such as mTOR, PI3K, AKT, RAF and MEK, and enhance the cytostatic effect of CDK4/6 inhibitors or the apoptosis of cancer cells." (PMID 35938171, 2022). "While CDK4/6 inhibitors have been approved for use in certain cancers, there are still patients who show no response to this therapy or develop resistance over time." (PMID 35525274, 2022). "Indeed, Palbociclib, also known as PD 0332991, a clinically approved CDK4/6 inhibitor, suppresses SEMA6C-low cancer cells more effectively, suggesting a druggable target in these cancers." (PMID 35269749, 2022). "Paclitaxel exhibits high activity against mitotic cells, but also can kill non-mitotic cancer cells, such as that are expected to accumulate in the presence of CDK4/6 inhibition." (PMID 36185294, 2022). "In addition, in this type of cancer, combined inhibition of CDK2 and CDK4/6 has enhaced sensitivity to palbociclib." (PMID 36266723, 2022). "Currently, whether CDK4 and/or CDK6 have direct regulatory effects on ABCB1 and ABCB1-mediated MDR in cancer, their roles, and mechanisms are unknown." (PMID 35459184, 2022). "A genome-scale CRISPR/Cas9 screen of 342 cancer cell lines revealed that AML cells are highly dependent on cyclin-dependent kinase 6 (CDK6) but not on its close homologue cyclin-dependent kinase 4 (CDK4)." (PMID 35326705, 2022).
cancer (continued). "The availability of CDK4/6i was one the most revolutionary events in the history of ABC treatment: for the first time, an improvement in OS in such a long natural history cancer population was observed, reaching so far one of the goals of Global Alliance against Cancer." (PMID 35330128, 2022). "Importantly, we found that both CDK4/6 protein degradation via LPM3770277 and CDK4/6 protein inhibition via abemaciclib lead to similar cell cycle arrest at G1 phase in TNBC cancer cells." (PMID 35479314, 2022). "Palbociclib, the first CDK4/6 inhibitor, was approved by the US Food and Drug Administration (FDA) as a therapeutic for estrogen receptor (ER)-positive metastatic breast cancer, and also exhibits pre-clinical efficacy in multiple cancers including NSCLC." (PMID 36005200, 2022). "The patient without a family history of cancer had several germline mutations: a pathogenic PALB2 mutation, and a VUS in ATM, MLH1, CDK4 and BRCA1." (PMID 36359225, 2022). "Low-dose DBP exposure revealed enhanced proliferation and expression of cell cycle genes (including cyclin-D, CCND1, Proliferating Cell Nuclear Antigen, PCNA, and cyclin-dependent kinase 4, CDK4) on prostate (PC3 and 22RV1) (10−6–10−7 M DBP) and breast (BG1) cancer cell lines (10−5–10−8 M DBP)." (PMID 35010832, 2022). "In contrast to our results with ribociclib, it has been reported that abemaciclib, a CDK4/6 inhibitor, did not significantly alter the expression of the P-gp transporter in cancer cells overexpressing the P-gp transporter." (PMID 35450042, 2022). "However, when the levels of pRb, as a reflection of CDK4/6 activity, were evaluated with respect to HER2 status, it was found that ER-negative and HER2-positive cancers had the highest level." (PMID 36387174, 2022). "The cyclin dependent kinase 4 (CDK4)-pRB-E2F1 axis has been shown to be essential for cell cycle progression in normal and cancer cells, and high expression of E2F1 has been found to promote the proliferation of cancer cells by transactivating cell cycle-related kinases." (PMID 36221072, 2022). "In HepG2 cells, abemaciclib alone downregulated p-p70S6K levels, supporting the finding that CDK4/6 inhibition reduces mTORC1 activity in some cancer models; however, no further decrease was observed with the combination." (PMID 35936714, 2022). "CDK4/6 and the AKT family of enzymes collaborate in a number of key cancer hallmarks, leading to the possibility that combined inhibition could be more efficacious as an anti-neoplastic therapy than either alone." (PMID 35158840, 2022). "In the presence of several types of pharmaceutical compounds (including CDK4/6i) to inhibit mitosis, paclitaxel was observed to induce micronucleation, suggesting a non-mitotic mechanism to break up the cancer nucleus." (PMID 36185294, 2022). "Furthermore, CDK4/6 inhibitors and PIK3CA inhibitors are standard of care for advanced luminal carcinomas, and ERBB2-low expression has been recently reported as an independent predictor of inferior progression-free survival." (PMID 36038884, 2022). "In addition, CDK4 inhibitor proteins, including p16INK4a (CDKN2A), are often inactivated in many cancers." (PMID 34930213, 2021). "In OncoKB but not the Cancer Gene Census, amplifications of CDK4 and BRAF are annotated as oncogenic whereas amplification of KRAS is likely oncogenic." (PMID 34313788, 2021). "Although there is still no available CDK4 inhibitor for HB, multiple selective CDK4 inhibitors targeting other types of cancer have been used in the clinic." (PMID 33868991, 2021). "Moreover, inhibiting the cell-cycle kinases CDK4 and CDK6 results in a significant therapeutic effect in several cancers." (PMID 33425489, 2021). "Despite potential efficacy demonstrated by in vitro and in vivo experiments, CDK4/6 inhibitors as single agents for cancer treatment do not appear to be very effective." (PMID 33806615, 2021). "Another CDK4 inhibitor, ryuvidine, has also recently shown efficacy in HPV- cancer cells." (PMID 34490123, 2021).
cancer (continued). "The recent clinical success of the inhibitors of CDK4 and CDK6 has convincingly demonstrated that targeting cell cycle components may represent an effective anti-cancer strategy, at least in some cancer types." (PMID 34204543, 2021). "CDK4/6 overexpression was found across multiple cancer types, many of which lacked CDK4/6 DNA/mRNA alterations." (PMID 34552204, 2021). "CDK4 and CDK6 inhibitors are now used in clinic for the treatment of patients with estrogen receptor positive metastatic breast cancer and their clinical use is being tested in many other cancer types, alone or in combination with other agents." (PMID 34204543, 2021). "High levels of LpCat1 in HCC could inhibit STAT1 expression, up-regulate CyclinD1, CyclinE, CDK4 and MMP-9, and decrease p27kip1 to promote cancer progression." (PMID 34178664, 2021). "CDK4/6 inhibitor resistance might be overcome by additional MEK inhibition, and several clinical trials of CDK4/6 inhibitors such as ribociclib or palbociclib with MEK inhibitors such as trametinib and bimetinib are currently ongoing in various cancer models." (PMID 33807122, 2021). "Overall, these findings suggest that CDK4 may play an crucial role in affecting the invasion and migration of HCC cells, and hence it may be used as a treatment target to suppress cancer metastasis in the future." (PMID 34784846, 2021). "In this model, expression of HRASG12V and Cdk4, which reflect Ras-MAP kinase activation as well as inactivation of the CDKN2A-mediated G1 restraints characteristic of cSCC, are sufficient to drive cancer progression by normal diploid epidermal keratinocytes." (PMID 34584216, 2021). "This study therefore discusses the cell cycle’s molecular mechanisms as well as the dysregulation in cancer, CDK structures, and drug complexes, as along with selected CDK inhibitors, including FDA-approved and currently undergoing clinical trial CDK4/CDK6 inhibitors." (PMID 34361615, 2021). "Among these, CDK4 and CDK6 inhibitors confirmed in clinical trials that CDKs might indeed represent valid therapeutic targets in, at least some, types of cancer." (PMID 34204543, 2021). "Like many targeted compounds used in cancer, CDK4/6is have not shown broad efficacy as single therapeutic agents." (PMID 34138895, 2021). "The top amplified cancer genes were KRAS, CDK4, BRAF, IL6, TLK2 and MITF." (PMID 34313788, 2021). "Interestingly, four of the six targetable genes, CDK4, RAD50, CHEK1, and MDM2, were involved in two or more major cancer-related pathways." (PMID 33557149, 2021). "Notably, mTOR is stimulated independently of the P13K signalling pathway by CDK4, through the phosphorylation of tumour suppressor folliculin (FLCN) and promotion of lysosomal function, leading to increased cancer cell survival." (PMID 34828525, 2021). "Thus, using targeted agents for DDR pathways, including inhibitors of ATR/CHK1, PARP, ATM, cyclin-dependent kinase 4/6 (CDK4/6), DNA-PK, WEE1, and aurora kinase B (AURKB) opens new exciting avenues for clinical development of ICB for cancer treatment." (PMID 34930377, 2021). "Among, 10953 patients/10967 samples of all type of human cancers publicly available in the online cancer genomic database cBioPortal, genetic alterations of CDK2/4/6 and STAT3 occurs in 825 (8%) patients, comprising 127 (1.2%) CDK2, 307 (2.8%) CDK4, 266 (2.4%) CDK6, and 220 (2%) STAT3 and." (PMID 33668805, 2021). "Similarly, recent evidence showed that chemical- or siRNA-based CDK4 and CDK6 inhibition can induce autophagy in multiple cancer cell lines." (PMID 34445095, 2021). "Although there are similarities between the effects of the distinct CDK4/6 inhibitors with regard to glycolysis and OXPHOS in some cancer models, there may also be drug-specific effects on metabolism, which also warrants further investigation." (PMID 33572972, 2021).